CD4 (CD4 molecule)
Diseases named in the same sentence as CD4 in open-access papers (continued):
Sharing a sentence is not in itself a finding about the gene and the disease.
tumor (continued). "We found that CD5 is commonly expressed on murine DC and has an inhibitory effect on the ability of DC to stimulate CD4 and CD8 T cells and to induce anti-tumor and contact hypersensitivity responses." (PMID 31491023, 2019). "The CD4+ T cells and CD8+ T cells populations in spleen, thymus, and tumor were reduced in CTX-treated groups while AS treatments did not resume the suppressed T cell populations." (PMID 31293425, 2019). "First, we monitored CD3+, CD4+, and CD8+ cells in the blood during tumor development by flow cytometry." (PMID 30972297, 2019). "In the induction phase of bacterial infection, the only responsible effectors for tumor clearance are CD8+ T cells, whereas during the memory phase the clearance involves CD8+ and CD4+T cells." (PMID 31771178, 2019). "These suppressive cells, under the coordination of the cancer cells, inhibit the functions of CD4+ and CD8+ T cells infiltrating the tumor." (PMID 31623629, 2019). "In univariate logistic analyses, high CD8+CD28+ T-cell counts (OR 0.12, 95% CI 0.03–0.48; P = 0.003), CD4/Treg ratio (OR 0.24, 95% CI 0.06–0.90; P = 0.035), and BED10 (OR 0.91, 95% CI 0.84–0.99; P = 0.032) predicted a 1-month tumor response to SABR." (PMID 30971280, 2019). "Flow cytometric analysis revealed that there was a significant increase in infiltration of both CD45+CD4+ T cells and CD45+CD8+ T cells upon tumor irradiation, which was further enhanced by blockade of PD-L1." (PMID 30987642, 2019). "In contrast, Treg cells suppress INFγ -expressing CD4+ Th1 cells and secrete VEGF via hypoxia-induced CCL28, that both promote an angiogenic tumor environment." (PMID 31572387, 2019). "To test if tumor-infiltrating T cells are responsible for tumor regression, we implanted αKO KPC cells in the pancreas of B6 mice whose T cells were depleted by injection of neutralizing antibodies to CD4 and CD8." (PMID 31112530, 2019). "The enhanced efficacy was associated with the increased CD8 + T cell, increased effector memory T cells (CD44 + CD8 + CD62L+), decreased Treg (CD4 + CD25 + Foxp3+) and M2 macrophages (F4/80 + CD206+) in the tumor microenvironment." (PMID 31882868, 2019). "CD4+ T helper, CD8+ CTLs, NK cells, M1 macrophages, and DCs are likely protecting against tumour growth whilst the CD4+ FOXP3+ Th2 cells, M2 macrophages, and myeloid-derived suppressor cells (MDSCs) simulate tumour growth." (PMID 31527531, 2019). "Our data using CD4KO and CD8KO mice indicate that both CD4+ and CD8+ T cells are essential for αKO KPC tumor regression." (PMID 31112530, 2019). "CD4+ and CD8+ T cell-depleting antibodies were used to understand the contribution of T cell-dependent anti-tumor immune responses." (PMID 30890189, 2019). "We obtained a core needle tumor biopsy 12 days after the first dose of AGEN1884, and isolated tumor infiltrating lymphocytes (TILs) by flow cytometry, with attention to CD8+, CD4+, and T regulatory cells." (PMID 31395100, 2019). "Our data show that 10% of CD4+ T and 18% of CD8+ T cells from tumor produce IFN-γ suggesting an activated phenotype." (PMID 32038621, 2019). "Compared with vaccination using HPV16 long E7 peptide in incomplete Freund’s adjuvant on its own, blocking IL-10 at the time of immunisation elicits significantly higher numbers of CD8+ T cells and attracts more CD4+ and CD8+ T cells to the tumour site." (PMID 31277636, 2019). "Studies have demonstrated that CD4 and CD8 T cells can inhibit tumor development and form tumor immunogenicity." (PMID 31534952, 2019). "We next analyzed by FACS the abundance of CD3+, CD4+, and CD8+ T cells in different tissues of tumor-bearing mice." (PMID 31214164, 2019). "CD4+ central memory T (TCM) cells maintain immune memory and exert immunoprotective effects during tumor metastasis." (PMID 32010623, 2019).
tumor (continued). "Based on the availability of autologous tumor specimens, we focused on NUP214 neoepitope-specific CD4+ T-cells obtained from TILs of Pt #19 and JAK1 neoepitope-specific CD4+ T-cells obtained from TILs of Pt #11." (PMID 31221207, 2019). "Both a high percentage (> 6%) of tumor infiltrating CD8+ T cells and a high CD4+ T-cell infiltration have been correlated to increased survival." (PMID 31261914, 2019). "Percentages of tumor cells (EpCAM+CD45-) in patients-derived spheroids and percentages of NK cells (CD3e-CD56+) and T cells (overall CD3+, CD4 T cells CD3+CD4+CD8-, CD8 T cells CD3+CD4-CD8+) in respective autologous TILs used for cocultures." (PMID 30871626, 2019). "Previous research on T-cells has long been focused on tumor-specific CD8+ CTLs because of their potent killing activity, while CD4+ T-cells have been studied primarily for their role as helpers to CD8+ CTLs." (PMID 30828566, 2019). "This immunosuppressive function is largely driven by CD4+/CD25+ Tregs, a subset of T cells that contribute to tumor progression and metastasis and correlates with poor patient prognosis." (PMID 31684144, 2019). "The ratio of CD8+/CD4+ T cells increased by CPA monotherapy for both primary and distant tumors, and this was also observed by MFA monotherapy, but only for the primary tumor." (PMID 31453050, 2019). "However, based on our finding that antigen-specific TCM was able to reject OVA-expressing skin graft and the ability of primed CD4 cells to facilitate tumor killing, we believe it is reasonable to speculate that these antigen specific TCM maintain at least indirect GVT activity." (PMID 31001254, 2019). "IHC staining for NF-κB, CD4, CD8, and PD-1 showed that the primary tumor contained a mixed population of NF-κB/p65RelA positive and negative cells, the presence of CD4+ and a low number of CD8+ cells, and no staining for PD-1." (PMID 31618954, 2019). "The combination of α-PD-1 and α-CTLA-4 can suppress tumor development by T cell infiltration into tumors and the induction of polyfunctional effector tumor infiltrating lymphocytes (TIL), probably CD4+ and CD8+ T cells." (PMID 30941374, 2019). "Another clinical study demonstrated that the percentage of TH22 cells in the CD4-positive T cell subset was significantly higher in CRC tissues, compared to that of para-tumor tissues, as determined by flow cytometry in patients with CRC." (PMID 31637216, 2019). "Herein, we establish the proof of principle that mouse natural cDC1s treated ex vivo with adjuvant and tumor-Ag for a very short time are efficient to induce Ag-specific anti-cancer CD8+ and CD4+ T cell responses in vivo." (PMID 30961656, 2019). "Both CD4+ and CD8+ T cells cultured with Raji or JeKo-1 tumor cells exhibited increased expression of the effector molecules Granzyme B and IFNγ." (PMID 31882897, 2019). "These stronger effects positively correlated with enhanced infiltration by CD4+ and CD8+ effector T cells: numbers of CD4+, CD8+, and IFN-γ+ CD8+ T cells in blood and tumor were higher in the GM-CSF/IL-21 group than in the other groups." (PMID 31467912, 2019). "Among tumor-infiltrating cells, we identified a population of lineage− (CD11b− CD11c− CD49b− Ly-6C− Ly6G− Ter119−) CD3+ CD4+ or CD3+ CD8+ T cells." (PMID 30696484, 2019). "In this trial, the DC were engineered with 3 full-length defined tumor antigens (tyrosinase, MART-1 and MAGE-A6) to activate multiple CD8+ and CD4+ T cell clones." (PMID 31014399, 2019). "Depletion of CD4+ T cells abrogated the anti-tumor efficacy of combination therapy with class II HER2-DC1 and anti-PD-1, suggesting that tumor regression was CD4 dependent." (PMID 31475002, 2019). "At day 15, DR500 tumor cells induced changes similar to those induced by MR20 cells (decrease in Gr1+D11b+ cells, increased in CD4+, CD8+ T and B lymphocytes) at the three sites, but to a lesser extent." (PMID 30546090, 2019).
tumor (continued). "The tumour cells circumvent the inherent immunological surveillance system by limiting the recognition by immune cells, including CD8+, CD4+ and natural killer (NKT) cells." (PMID 30893948, 2019). "TIM3, a potent T cell suppressor of the immune response, was found to be significantly overexpressed in the lymph node and splenic CD4+ and splenic CD8+ T cells of metastatic Stat4−/− mice compared to tumor bearing WT mice." (PMID 32010142, 2019). "Furthermore, tumor antigen specific CD4+ T effector cells can essentially sustain anti-tumoral immune responses as shown for various tumor entities, thus suggesting that cognate interaction between tumor antigen-specific CD4+ Th1 cells and TAMs might shift the intra-tumoral M1/M2 ratio toward M1." (PMID 30853959, 2019). "Tumor infiltrating CD8+ and CD4+ T cells remain an important predictor of patient outcomes and responsiveness to anti-PD-1 therapy, with recent discoveries highlighting a role for TCF7+CD8+ T cells in predicting responsiveness." (PMID 30857561, 2019). "To investigate the effects of innate and adaptive immunity on the final antitumor immune responses, we depleted CD4+, CD8+ and NK cells with a monoclonal antibody at 14 days after tumor cell inoculation and surgery in the 4T1 tumor model." (PMID 31431623, 2019). "To determine if differential killing of tumor cells is associated with differences in CD20xCD3-induced T cell effector function, we assessed CD4+ and CD8+ T cell activation in co-culture with Raji, JeKo-1, and RL tumor cells." (PMID 31882897, 2019). "Increased infiltration of CD4 + and CD8 + T cells, in addition to macrophages, into the tumor space and increased expression of PD-L1 in the tumor by co-administration of bevacizumab and sunitinib have been shown in the RCC mouse model." (PMID 30845711, 2019). "Although percentages of most immune cells were not affected after different vaccine treatments, a significantly higher proportion and number of CD4+ and CD8+ T cells were observed in TILs after treatment with LX/IL-24-modified tumor vaccines." (PMID 31338417, 2019). "Tumour effect accounted for 54.1%, 53.7% and 55.5% of total variance in lymphocyte counts for CD3, CD4 and CD8 respectively, while block effect contributed to only 0.3%, 0.5% and 0.7% total variance for the same respective markers." (PMID 31601875, 2019). "Based on this limited set of samples, IR+ OPSCC tumors contained higher percentages of highly activated PD1hiHLA-DRhi CD4 and CD8 T cells, and their levels correlated with the number of tumor-infiltrating TbethiTregs." (PMID 30658697, 2019). "We also assessed the number of HLA-1+ tumor cells, CD3+, CD20+, CD8+PD1 and CD4+FOXP3+ cells, per each tumor cell within the CD3+ cell neighborhoods within IAs." (PMID 31166985, 2019). "Treg (CD4+CD25+) cells purified both from spleen and pancreas of tumor-bearing mice were incubated with tumoral MDSCs and the co-cultures monitored every 20 min." (PMID 32038621, 2019). "(C) Ki-67+ CD4 and CD8 T cells of tumor bearing CCSP-rtTA; TetO-EGFRL858R mice in the absence (−) and presence (+) of erlotinib for 2 weeks or mice taken off doxycycline for 2 weeks." (PMID 31291990, 2019). "We then calculated the ratio of pro-tumor immune cells (MDSCs, TAMs and Tregs) to anti-tumor immune cells (IFN-γ+ CD8+ and Foxp3− CD4+) as an indicator for the overall immune balance within the tumor microenvironment." (PMID 31015520, 2019). "It has been shown to be expressed by CD4+ and CD8+ T-cells, Tregs, DC, NK-cells, monocytes, macrophages and granulocytes, as well as tumor cells." (PMID 31060337, 2019). "Tumor-infiltrating CD4+ T cells showed the highest relative ratio of ST2-expressing cells and a substantial proportion of CD4+ T cells in CRC lesions were FOXP3+ Tregs." (PMID 31165767, 2019). "In brief, CD4+ T helper, CD8+ CTLs, NK cells, M1 macrophages, and DCs are protective against tumour growth." (PMID 31527531, 2019).
tumor (continued). "We observed in vitro stimulation of E7-peptide or induced IFN-γ production by CD8+ or CD4+ T cells, respectively, in immunized mice, which implies the role of CD8+ T cells and CD4+ T cells in anti-tumor activity." (PMID 30875953, 2019). "In contrast, in IAs from less immune-infiltrated tumors, neighborhoods centered by CD3+ T cells contain higher numbers of CD20+ and CD4+FOXP3+ cells per each tumor cell and less HLA1+ tumor cells, favoring potential immunosuppressive environment." (PMID 31166985, 2019). "Similar to what we observed in tumours, RTCT increased rectal CXCR4 expression and the accumulation of immune cells, including T-cells (CD4, CD8), MDSCs (Ly6G) and macrophages (F4/80)." (PMID 31239542, 2019). "TNFα‐CSG therapy was ineffective in BALB/c nude mice, and transfer of normal CD8+ and CD4+ T cells into these mice restored the ECM degradation and anti‐tumour effects." (PMID 31709774, 2019). "Their specific loss leads to larger tumors that exhibit reduced infiltration of both CD4+ and CD8+ T-cells, despite the fact that T-cell priming appears to be normal in tumor-bearing BATF3-/- mice." (PMID 31188899, 2019). "Depletion of NK cells in α-GalCer-treated mice showed a lower frequency of IFN-γ-producing CD4+ and CD8+ T cells in the tumor and prevented the α-GalCer-induced tumor growth." (PMID 31387637, 2019). "Long peptide vaccines which contain both T cell epitopes for HLA Class I molecules and HLA Class II molecules have shown promise in eliciting both CD4 and CD8 T cell immunity against tumor cells expressing viral or tumor antigens." (PMID 31722672, 2019). "CD19+ Tim‐1+ cells down‐regulated the function of effector CD4+CD25low T cells ex vivo dependent on IL‐10 production, and adoptive transfer of CD19+ Tim‐1+ cells promoted tumour growth in mice." (PMID 30467955, 2019). "Flow cytometric analyses of TILs revealed that L-NAME combined with an anti-PD-1 blockade tended to decrease tumor-infiltrating CD4+FOXP3+ regulatory T cells, and significantly increased the CD8+/CD4+FOXP3+ ratio in MCA205WT tumors." (PMID 31481761, 2019). "Mice treated with this combination immunotherapy displayed higher numbers of tumor-infiltrating CD8+ and CD4+ T cells and reduced T regulatory cells in tumors." (PMID 31428586, 2019). "Depletion experiments revealed that, during induction phase, CD8+ T cells are the sole effectors responsible for tumour clearance while in the memory phase CD8+ and CD4+T cells were involved." (PMID 31183361, 2019). "We identified a peculiar aspect of Npos PDAC tumor propensity in educating the immune surveillance, reducing effector CD8 and CD4 T cells." (PMID 31277479, 2019). "Both tumor-infiltrating CD8+ and CD4+ T cells express PD-1, and the proportion of PD-1-positive T cells decreased modestly upon ablation of IL-17 signaling." (PMID 31775909, 2019). "Thus, activation of these cells could be an effective anti-tumor immunotherapy, which has been proven by clinical observation showing that high levels of CD8+ and CD4+ T cells are associated with improved survival in breast, head and neck, colon, and lung cancer." (PMID 31297335, 2019). "Moreover, the concomitant reduction in St2−/− mice of tumor load and CD4+ FOXP3+ Tregs and the findings that Treg-restricted St2 ablation is associated with reduced CRC development led us to hypothesize that ST2+ CD4+ FOXP3+ Tregs support CRC development." (PMID 31165767, 2019). "Our results showed comparable correlations between CD4/Treg ratio and CD8/Treg ratio and the tumor response after SABR." (PMID 30971280, 2019). "CD8+ effector T-cells (CD3+ CD4- CD8+ Tbet+) and effector memory T-cells (CD3+ CD4- CD8+ Tbet+ Eomes+) are essential to tumor cell killing and immunological memory, respectively." (PMID 31863071, 2019). "Absolute number of (C) CD4 and (D) CD8 T cells normalized to weight of lungs of control (normal) and tumor bearing CCSP-rtTA; TetO-EGFRL858R mice in the absence (−) and presence (+) of erlotinib for 2 weeks." (PMID 31291990, 2019).
tumor (continued). "When upregulated on CD4+Foxp3+ T cells, TIGIT induces the expression of IL-10, contributing to dysfunctional CD8+ T cells within tumor microenvironments." (PMID 31616431, 2019). "In LIHC and THYM, our results showed a strongest correlation of UHRF1 expression and immune infiltration level, including tumor purity, B cell, CD8+ cell, CD4+ cell, macrophage, neutrophil and dendritic cell." (PMID 31442209, 2019). "As such the strong tumor-specific infiltration of HPVnegVSCC with activated CD8+ (population 1) and CD4+ (population 7) effector T cells sustains the notion these tumors are immunogenic and explain why their presence is associated with better clinical outcome." (PMID 31481117, 2019). "Tumor cells, via overexpressing COX2 and elevating PGE2 production, favor the development of a Treg phenotype in human and mouse CD4+ T cells." (PMID 30913212, 2019). "This patient also showed increasing Ki67+ CD4+ and CD8+ T cells along with the upregulation of antitumor gene expression localized to the tumor after IT1208 administration." (PMID 31340866, 2019). "Analysis of host T cells demonstrated significant PD-1 upregulation on normal host T cells, both CD4 and CD8, in syngeneic mice bearing T-ALL5 relative to non-tumor-bearing C57BL/6 controls and a trend toward increased PD-1 expression in mice bearing T-ALL3." (PMID 31399482, 2019). "When comparing high HLA-1 tumor-containing TME with low HLA-1 tumor-containing TME, we observed differences in CD4+ and CD8+ TILs." (PMID 31166985, 2019). "After NIC treatment compared to free mAbs, both flow cytometry and immunohistochemistry showed an increase in effector T cells (CD4+ and CD8+) that can mediate tumor attack." (PMID 31462642, 2019). "Given that gemcitabine alone had a negligible effect on intra-tumoral CD4:CD8 levels, these data suggest the recruitment and expansion of CD8+ T cells inside the tumor was largely the result of STING activation." (PMID 31036082, 2019). "Of key importance in immune surveillance is the recruitment of dendritic cells (DCs), CD4+Th1 cells, and CD8+ T effector cells to the tumor microenvironment." (PMID 30873179, 2019). "Flow cytometry analysis demonstrated the expression of inhibitory receptor PD-1 on CD4+ and CD8+ T cells and its ligand PD-L1 on tumor cells in CT-2A-dmEGFRvIII-Luc and SMA560-dmEGFRvIII-Luc tumors." (PMID 31142380, 2019). "Immunohistochemistry for CD4, CD8, Foxp3, Granzyme B (GZMB), PDL1, and HLA class I was performed in tumor biopsies collected before and after DC vaccination." (PMID 31649669, 2019). "An increased frequency of CD4+ and CD8+ T cells and a decreased level of IL-6 in tumor tissue were also found." (PMID 30959898, 2019). "Expression of the Cxcl9/Cxcl10 receptor Cxcr3 was increased in HKMTI-1-005-treated cohort tumours on CD8+[mean fluorescence intensity (MFI) 3959 vs2097, p<.0001], CD4+(MFI 2341 vs1099, p<.0001)and NK (MFI 1507 vs440, p<.0001) cells." (PMID 31591445, 2019). "Mechanistically, these dual therapies are more effective than corresponding monotherapies at increasing the intra-tumoral presence of tumor-specific CD8+ T cells, CD4+FoxP3neg T cells as well as the levels of IFNγ and of mRNA coding for IFNγ and T-bet." (PMID 31244820, 2019). "As observed by flow cytometry, the amount of CD4+ cells increased significantly as well as CD3+ and Nkp46+ cells with Pirfenidone treatment within the tumor tissues, whereas CD19+ cells were unaffected by the treatment." (PMID 32039023, 2019). "We next examined the cytotoxicity of splenic CD4+ T cells and CD8+ T cells against tumor cells in vitro by a CCK-8 assay." (PMID 30833570, 2019). "Our findings from in vitro functional studies and from transcriptomic analyses of tumor tissues and CRC-isolated Tregs also indicate an implication of the IL-33/ST2 axis in the regulation of IL-17A expression by FOXP3+ Tregs and FOXP3− CD4+ T cells." (PMID 31165767, 2019).